SAMHD1 (SAM and HD domain containing deoxynucleoside triphosphate triphosphohydrolase 1)
Diseases named in the same sentence as SAMHD1 in open-access papers (continued):
Sharing a sentence is not in itself a finding about the gene and the disease.
infection (179 papers, 2011 to 2026). The state of being infected such as from the introduction of a foreign agent such as serum, vaccine, antigenic substance or organism. "While epithelial cells represent a key target for HSV-1 infection, immune cells such as macrophages are also susceptible to infection and key restriction factors, such as SAMHD1, have been reported to exert anti-HSV-1 activity in macrophage-like cells." (PMID 40780411, 2025). "The results demonstrated that the activation of NF-κB in macrophages was responsible for the high resistance of Samhd1-deficient larvae to STM infection." (PMID 40352920, 2025). "Next, we asked if SAMHD1 deficiency suppressed ΔS-VRP(G) infection similarly as that observed in the authentic SARS-CoV-2 infections." (PMID 41280104, 2025). "To further validate the role of NF-κB in the resistance of Samhd1-deficient larvae to infection, we treated the larvae with BAY11-7082, an NF-κB inhibitor, and conducted a challenge with STM." (PMID 40352920, 2025). "Larvae with macrophages expressing DN-Nfkbiaa lost their hyperresistance to infection, behaving similarly to control larvae, indicating that the activation of NF-κB in Samhd1-deficient macrophages is essential for their enhanced resistance to STM infection." (PMID 40352920, 2025). "Downregulation or loss of SAMHD1 expression augments the susceptibility of myeloid-derived cells or resting CD4 + cells to infection." (PMID 39871364, 2025). "In this context, we performed a challenge against STM in which the Samhd1-deficient larvae were more resistant to the infection." (PMID 40352920, 2025). "Collectively, these findings indicate that Samhd1-deficient larvae display a heightened inflammatory state, facilitating a more robust and accelerated response to pathogen infection compared with control larvae." (PMID 40352920, 2025). "Mechanistically, pharmacological inhibition of SPHK reduced susceptibility to infection primarily by downregulating phosphorylated SAMHD1 (pSAMHD1), enhancing the activity of this innate HIV-1 restriction factor." (PMID 35412343, 2022). "In this work, we report that inhibition of sphingosine kinases reduces the susceptibility of CD4 T cells to infection primarily via modulation of SAMHD1 phosphorylation." (PMID 35412343, 2022). "The increased infection in CD4+ T cells stimulated with IL-15 was associated with an almost 10-fold increase in the phosphorylation of SAMHD1 on threonine 592 that abrogates its restriction activity." (PMID 35499323, 2022). "Recently, we found that also the MCMV orthologue of pUL97—M97—strongly phosphorylates murine SAMHD1 at T603 upon infection of murine macrophages, causing the loss of its antiviral activity." (PMID 33801276, 2021). "This is evident when gene silencing of SAMHD1 in macrophages/DCs raises their susceptibility to infection by Vpx-deficient virus." (PMID 34697376, 2021). "Jáuregui and Landau postulated that the Growth of MDMs under conditions that alter the cell cycle alters SAMHD1 phosphorylation and affects their susceptibility to infection by HIV-1." (PMID 32375558, 2020). "Compared to Towne or Toledo-infected cells, JHC-infected cells showed a decrease of SAMHD1 level from 48 h after infection, although the complete loss of SAMHD1 was observed at 96 h after infection, as in other laboratory strains." (PMID 32850489, 2020). "In an effort to study the role of SAMHD1 in cccDNA formation at earlier time points following infection, we used a recombinant HBV reporter virus encoding Gaussia luciferase (rHBV-Gaussia) where luminescence is dependent on cccDNA formation." (PMID 30918010, 2019). "Retroviral restriction by cysteine mutants was evaluated in PMA-treated U937 cells stably expressing the different SAMHD1 variants that were challenged with increasing amounts of HIV-1 virus expressing GFP as a reporter of infection." (PMID 30044979, 2018).
infection (continued). "The block to infection resulted from a decrease in phosphorylated SAMHD1, which was associated with an increase in p21 levels." (PMID 29515139, 2018). "Growth of MDMs under conditions that alter the cell cycle, including culturing the cells in medium containing FBS or PHS37 or with M-CSF or GM-CSF33 alters SAMHD1 phosphorylation and affects their susceptibility to infection by HIV-1." (PMID 29515139, 2018). "The block to infection was at reverse transcription and was counteracted by Vpx, demonstrating that it was caused by SAMHD1." (PMID 29515139, 2018). "Depletion of SAMHD1 in macrophages decouples the association between infection and expression of cell cycle‐associated proteins, with terminally differentiated macrophages becoming highly susceptible to HIV‐1." (PMID 28122869, 2017). "Critically, degradation of SAMHD1, through co‐infection with SIVmac VLP‐vpx, or SAMHD1 depletion using RNAi, completely abrogated the association between infection of MDM and MCM2 expression (and EV4C)." (PMID 28122869, 2017). "Advantage was taken ofthe finding that simian immunodeficiency virus (SIV)/HIV-2 encoded Vpx has theability to overcome the restriction to infection posed by SAMHD1, which hydrolysesdNTPs needed for HIV-1 reverse transcription." (PMID 28113052, 2017). "Some lentiviruses have evolved countermeasures against SAMHD1; for example, the HIV‐2/SIVsm lineage encodes the Vpx protein that degrades SAMHD1 and allows infection of otherwise SAMHD1‐positive target cells." (PMID 28122869, 2017). "We further show that SAMHD1-deficient myeloid cells produce heightened levels of IFNs in response to infection with VSV-G-pseudotyped HIV-1-derived lentiviruses and are activated more strongly." (PMID 27477283, 2016). "To determine at which step in the viral life cycle HIV-1 is sensed in SAMHD1-deficient myeloid cells, we treated BMMCs with the RT inhibitor nevirapine or the integrase inhibitor raltegravir during infection with FGLenti-RTV148I." (PMID 27477283, 2016). "The block to infection was strongly induced in mouse SAMHD1 knock-out BMDCs which are otherwise highly susceptible to HIV-1." (PMID 27905985, 2016). "This efficient infection was associated with a potent down-regulation of SAMHD1 in up to 90% of the cells." (PMID 25582927, 2015). "This enhanced infection of DCs using HIV-C was accompanied by a highly phosphorylated status of SAMHD1 T592, which was associated with relieved HIV-1 restriction and higher induction of cellular and type I IFN immune responses." (PMID 26121641, 2015). "PMA-treated U937 cells stably expressing SAMHD1 variants were challenged with increasing amounts of HIV-1 virus expressing GFP as a reporter of infection." (PMID 24219908, 2013). "As NFKB protects murine models from STM infection and this pathogen is able to hijack NF-κB with its effector protein SpvB, we next studied whether Samhd1-deficient zebrafish larvae were more resistant to STM infection than their WT counterparts." (PMID 40352920, 2025). "The results confirmed this hypothesis, showing that Samhd1-deficient zebrafish larvae were more resistant to STM infection, with almost a 30% higher survival than WT larvae." (PMID 40352920, 2025). "Finally, the transcript levels of cxcl8a were unaffected by Samhd1 deficiency independently of infection." (PMID 40352920, 2025). "In addition, the expression of the il1b and isg15 transcripts also increased in Samhd1-deficient larvae following infection." (PMID 40352920, 2025). "However, regarding arboviruses replication, up-regulation of SAMHD1 is positively associated with harmful infection." (PMID 34490131, 2021). "Since the aberrant nuclear localization pattern of SAMHD1 found at late times of infection resembles viral replication compartments, we tested whether SAMHD1 is associated with these sites." (PMID 32850489, 2020).
infection (continued). "The complement-mediated SAMHD1 phosphorylation was associated with significantly enhanced DC infection, DC activation as well as aberrant type I interferon expression, pro-inflammatory responses and stronger induction of cytotoxic T cell induction by complement-HIV-exposed DCs." (PMID 33224139, 2020). "We concluded that the block to infection induced by NCS is caused by SAMHD1." (PMID 29515139, 2018). "Notably, we found that antigen-specific CD8 T cell responses were up to 10-fold stronger in Samhd1−/− mice compared to wild-type controls upon infection with the SIINFEKL-encoding lentivirus." (PMID 27477283, 2016). "Comparing the susceptibility to infection with intracellular dNTP levels and SAMHD1 phosphorylation in different cell types shows that both functions are important determinants of the antiviral activity of murine SAMHD1." (PMID 26667483, 2015). "Clearly, the single-round infection system used in the present study meant that well-known retroviral auxiliary proteins were not encoded; therefore, they cannot be involved in determining SAMHD1-mediated retroviral specificity." (PMID 26032178, 2015). "These opposing observations implicate SAMHD1 as a target for HIV-1 drug intervention either through the enhancement of SAMHD1 activity to reduce cell susceptibility to infection or through cell-targeted inhibition of SAMHD1 to promote a more robust immune response." (PMID 25331707, 2015). "Because SAMHD1 directly targets retroviral genomic RNAs at early time points following infection, we examined whether retroviral RT, a hallmark of retroviral infection, is required for the retroviral specificity of SAMHD1." (PMID 26032178, 2015). "Some rare macrophages may end up with particularly low levels of SAMHD1 based on stage of differentiation, source, history, and activation state and these may be weakly susceptible to infection by vpx-deleted SIV." (PMID 24465411, 2014). "Unexpectedly, infection levels in wild-type and SAMHD1-deficient cells in vitro and in mice in vivo were identical, in contrast to what had been observed in human cells depleted of SAMHD1 and infected with the same or very similar lentivectors." (PMID 24854580, 2014). "Treatment with MLN4924, however maintained SAMHD1 levels despite infection with Vpx-encoding HIV-2." (PMID 24245672, 2013). "Therefore, infection by lentiviruses encoding a SAMHD1 antagonist (either Vpx or Vpr) might lead to increased replication of endogenous retroelements and a possible impact on host genome stability." (PMID 24782834, 2014). "Some viruses escape SAMHD1 restriction and utilize SAMHD1-mediated innate immune suppression to establish effective infection through IFN antagonism." (PMID 41855156, 2026). "In summary, this study is the first to reveal that Samhd1 plays a crucial role in restricting the macrophage-mediated clearance of STM infection." (PMID 40352920, 2025). "Some viruses escape SAMHD1 restriction by utilizing SAMHD1-mediated innate immune suppression to establish effective infection through viral antagonism." (PMID 41280104, 2025). "Accordingly, the infectivity of SIVmac239-WT-GFP was found to be significantly increased in the USP37 knockdown group, indicating that USP37-knockdown led to more unstable SAMHD1 upon SIVmac239 infection." (PMID 39655951, 2025). "Consistently, we found that reconstitution of SAMHD1 expression in SAMHD1 KO cells reinforced cytosolic release of Cyto c in the absence or presence of HIV-1-Luc/VSV-G infection to the level comparable to THP-1 Ctrl cells." (PMID 40434097, 2025). "In non-dividing cells of the myeloid lineage and in resting CD4-positive T cells, SAMHD1 restricts the infection of human immunodeficiency virus type 1 (HIV-1)." (PMID 40352920, 2025). "Consistent with increased Vpx stability, SAMHD1 was degraded more efficiently in VHL-knockdown cells following infection with wild-type HIV-2-Luc compared to control cells." (PMID 40522994, 2025).
infection (continued). "Expression of several restriction factors, of which SAMHD1 is well known, limits productive infection." (PMID 40029073, 2025). "SAMHD-1 expression remained unaltered throughout the experimental period, potentially to support DNA repair mechanisms activated in response to infection, as an adequate dNTP supply is essential for DNA synthesis." (PMID 40429613, 2025). "For example, expression of genes encoding for DDX58/RIG-I, USP18, SAMHD1, and several members within the IFIT family was greater in response to SARS-CoV-2 than SARS-CoV-1 infection." (PMID 39874350, 2025). "Our present results, as well as previous findings on SAMHD1, indicate that macrophage cell-to-cell infection by cell-cell fusion with infected T cells escapes restriction by IFN-stimulated or IFN-independent restriction factors." (PMID 40294108, 2025). "This correlates with our reasoning of high SAMHD1 expression in CD11c+ ASDCs which reduces their productive infection compared to CD123+ ASDCs expressing lower SAMHD1." (PMID 38924030, 2024). "Infection of VV Ankara in human dendritic cells is enhanced when SAMHD1 is degraded by simian immunodeficiency virus (SIV) viral protein X (Vpx), restoring VV late gene expression." (PMID 39339888, 2024). "We generated human U937 cells that stably expressed these SAMHD1 variants and challenged these cells with increasing amounts of an HIV-1 construct that expresses green fluorescent protein (GFP) as an infection reporter." (PMID 39162568, 2024). "For example, despite being dispensable for replication in many non-myeloid cell lines, Vpx is required for efficiently spreading infection in peripheral blood lymphocytes wherein SAMHD1 is primarily in the inactive state." (PMID 39205287, 2024). "The inhibitors were added to infected or uninfected A549 cells, and SAMHD1 and NP protein levels were detected 24 h after infection." (PMID 38287375, 2024). "The cellular SAMHD1 was significantly upregulated in human skin fibroblasts upon infection with the Zika virus." (PMID 39339888, 2024). "In support of this observation, when HU was added to the cycling cells during infection, replication was completely abolished in cells expressing catalytically active WT SAMHD1 and Tetstable mutants." (PMID 37127613, 2023). "In contrast, VLP-Vpx-mediated depletion of SAMHD1 D218A mutants allowed higher infection levels, which after depletion were similar to SAMHD1 KO cells." (PMID 37800914, 2023). "Vpx and SIV Vpr assemble with DCAF1 (also known as VPRBP) a substrate receptor for Cullin 4 CRL (Cullin Ring ubiquitin ligase) and target SAMHD1 for degradation, allowing for productive infection to occur." (PMID 37766341, 2023). "Lentiviral infection of human resting T cells in culture was shown to be restricted by SAMHD1, consistent with this finding." (PMID 35972807, 2022). "SAMHD1 degradation was detected in DCs exposed to HIV-2 despite the failure of the virus to establish infection." (PMID 35073912, 2022). "To rule out the impact of endogenous SAMHD1 and accentuate the antiviral activities of SAMHD1 truncations and mutants, we transfected plasmids expressing SAMHD1 truncations and mutants in SAMHD1-KO Huh7.5.1 cells followed by infection with JFH1 HCVcc." (PMID 36532074, 2022). "After differentiation into macrophages, the SAMHD1 knock-out cells exhibited 50-fold increased infection with HIV-1." (PMID 36015010, 2022). "In contrast, in vitro experiments in primary monocytes showed that the expression of SAMHD1 induced an abortive infection by HTLV-1, which then triggered a STING-dependent apoptosis due to the accumulation of DNA replication intermediates." (PMID 35893677, 2022). "The genomes of HIV-2 and some SIV strains contain the accessory gene vpx, which carries out several functions during infection, including the downregulation of SAMHD1." (PMID 33563288, 2021).
infection (continued). "It has been shown that complement-opsonized HIV-1 binds to CR3 and CR4 present on monocyte-derived DCs35 leading to infection of immature DCs by overcoming SAMHD1 restriction." (PMID 33568786, 2021). "Identification of SAMHD1 as the factor that impedes infection of myeloid cells by HIV and SIV brought to light an intrinsic cellular antiviral immunity mechanism that relies on controlled reduction of deoxynucleotide triphosphate (dNTP) availability." (PMID 33531504, 2021). "SAMHD1 impedes infection of myeloid cells and resting T lymphocytes by retroviruses, and the enzymatic activity of the protein—dephosphorylation of deoxynucleotide triphosphates (dNTPs)—implicates enzymatic dNTP depletion in innate antiviral immunity." (PMID 33531504, 2021). "SERINC5, BST2, APOBEC and SAMHD1 are some of those factors highly ubiquitinated and therefore targeted to their degradation by viral proteins or under conditions of infection." (PMID 34835003, 2021). "SAMHD1 prevents the infection of host cells by retroviruses, including HIV, via depletion of the cellular dNTP pool available for viral reverse transcription." (PMID 34697376, 2021). "Sze and colleagues reported that infection of human T cell leukemia virus 1 (HTLV-1) was abrogated in primary macrophages by SAMHD1 through activation of a STING-mediated apoptosis pathway." (PMID 33801276, 2021). "A dose-dependent increase in infection levels was observed, and infection in the presence of VLPVpx was higher than in its absence as expected, due to the restrictive activity of SAMHD1 following PMA-differentiation." (PMID 33563288, 2021). "Overcoming SAMHD1 restriction in MDMs to achieve equal infection levels uncover an innate immune signaling enhancer activity of Vpx, which likely depends on the targeting of a host protein for degradation." (PMID 33563288, 2021). "At equal input of Vpx− and Vpx+ viruses, a pronounced difference in infection was observed, concomitant with SAMHD1 degradation." (PMID 33563288, 2021). "This leaves the question unanswered, if in a physiological setting, upon host cell infection, Vprmus first captures SAMHD1 to guide it to the CRL4 complex, or if it hijacks CRL4 to subsequently recruit SAMHD1." (PMID 34339457, 2021). "Infection of WT and SAMHD1 KO mice revealed an enhanced replication of MCMV in SAMHD1 KO mice, showing for the first time that SAMHD1 acts as an antiviral restriction factor against a replicating virus in vivo." (PMID 33801276, 2021). "Sterile alpha motif and HD domain 1 (SAMHD1) is a deoxynucleotide triphosphohydrolase (dNTPase) that restricts the infection of a variety of RNA and DNA viruses, including herpesviruses." (PMID 34238351, 2021). "In the presence of SAMHD1 (untreated cells), vDNA synthesis continued even after 4 days post-infection." (PMID 33143125, 2020). "We found that SAMHD1 protein level is initially upregulated after infection, but it is downregulated at late stages of infection." (PMID 32850489, 2020). "The SAMHD1 enzyme restricts infection by degrading the pool of nucleotides available for viral reverse transcription." (PMID 32656092, 2020). "In particular, the constitutive expression of SAMHD1 detected in uninfected HFFs was significantly upregulated upon infection with either AD169, VR-1814 or TR, or fresh primary HCMV isolates collected from infants with congenital infection." (PMID 32986788, 2020). "We show that SAMHD1 expression was upregulated after infection, but with only a modest effect in limiting viral replication." (PMID 32986788, 2020). "The ILC2s of Cluster 14 expressed Cor1a, Samhd1, Ccl1 (monocyte chemotaxis), Arg1 (promotes acute type 2 inflammation), and C1qbp (involved in multiple infection and inflammatory responses)." (PMID 32351546, 2020). "In this study, we investigated how SAMHD1 expression is regulated during productive infection in primary HF cells." (PMID 32850489, 2020).